RYR1 (ryanodine receptor 1)
Diseases named in the same sentence as RYR1 in open-access papers (continued):
Sharing a sentence is not in itself a finding about the gene and the disease.
heart failure (14 papers, 2012 to 2026). Inability of the heart to pump blood at an adequate rate to meet tissue metabolic requirements. "Downregulation of RyRs activity has been found in diseases involving loss-of-function mutations (RyR1-related diseases and RyR2 calcium release deficiency syndrome) and reduced expression of RyRs (myopathies, sarcopenia, heart failure, cardiomyopathies, ICU muscle weakness, and others) (13, –15)." (PMID 40512792, 2025). "For example, Brody myopathy characterized by mutations in SERCA1 leads to muscle weakness, Darier disease characterized by mutations in SERCA2 is associated with increased risk of heart failure, and ryanodine receptor 1 related myopathies are associated with muscle weakness and atrophy." (PMID 37133648, 2023). "In fact, several mutations in RyR1 and RyR2 proteins cause decreased affinity between RyRs and calstabins, leading to abnormal calcium cycling, a major hallmark of several cardiac phenotypes, including heart failure." (PMID 22236651, 2012). "RyR1 OE mice had increased whole heart, left ventricular weight, and left ventricular wall thickness, but decreased cardiac output and stroke volume, thereby presenting CH and heart failure (HF)." (PMID 42196272, 2026). "This alignment strengthens the potential role of RYR1 in heart failure progression." (PMID 40060969, 2025). "Ryanodine receptor 1, RYR1, plays a role in regulating calcium channel opening and is behind the pathological mechanism involved in muscle weakness and impaired physical activity observed in patients with heart failure." (PMID 37626628, 2023). "Carvedilol, a beta-blocker commonly used to treat and manage heart failure and cardiac arrhythmias, suppresses store overload-induced calcium release (SOICR) in HEK-293 cells expressing MH/CCD-associated RYR1 variants in different regions of the RyR1 channel, including leaky N-terminal variants." (PMID 30406384, 2018). "We propose that xanthine derivatives and analogs that enhance RyRs activity could be used for lead optimization and eventually for the treatment of the diseases that exhibit decreased muscle contraction and reduced RyRs activity, such as RyR1-related diseases, sarcopenia, and heart failure." (PMID 40512792, 2025). "It has been reported that phosphorylation of the S2843 residue of RyR1 by PKA dissociates FKBP12 from the receptor, and phosphorylation and dissociation of FKBP12 were also observed in an animal model of heart failure." (PMID 34639137, 2021). "Among these, the group of ryanodine receptor‐1‐calstabin complex stabilizers (RYR‐stabilizers) is mentioned, which is being investigated as a potential treatment option for Ryanodine receptor 1 (RYR 1)‐related myopathies, heart failure, cardiac arrhythmia, and Duchenne muscular dystrophy." (PMID 41454756, 2026). "Moreover, although inhibition of the RyR2 channel in the heart could be a promising anti-heart failure or anti-CPVT1 approach, it could give rise to serious extra-cardiac side-effects because of a strong inhibitory effect of dantrolene on RyR1 and RyR3 channels." (PMID 36982484, 2023).
muscle disorders (12 papers, 2014 to 2025). "RYR1-related myopathy is a class of rare muscular diseases due to heterozygous or homozygous mutations in RYR1, which encodes the Ca2+ channel RYR1." (PMID 36450915, 2022). "Muscle disorders linked to RYR1 mutations in humans range in clinical presentation from malignant hyperthermia to core myopathies to congenital fiber type disproportion." (PMID 31383689, 2019). "Core myopathies are a group of childhood muscle disorders caused by mutations of the ryanodine receptor (RyR1), the Ca2+ release channel of the sarcoplasmic reticulum." (PMID 29701772, 2018). "Inactivation of this protein is lethal at birth in mice and mutations of the RYR1 gene in humans are associated various muscle disorders." (PMID 26200109, 2015). "It has been known that dominant and recessive mutations in RYR1 could cause a range of muscle disorders, though many other aspects of disease pathogenesis involving this gene remain uncertain." (PMID 27353517, 2016). "Although further work is required, our data suggest that the drug might play a role in the treatment or management of additional RYR1-associated human or animal myopathies or other muscle disorders with primary or secondary defects in calcium homeostasis." (PMID 25148524, 2014). "The affected individuals essentially manifested neonatal or infancy-onset hypotonia, delayed motor milestones, and a benign disease course differing from classical RYR1-related muscle disorders." (PMID 34535181, 2021). "Myopathies related to Ryanodine receptor 1 (RYR1) mutation are the most common nondystrophy muscle disorder in humans." (PMID 35692882, 2022). "Thus, we provide an intriguing perspective of involvement of mis-regulated RyR1 splicing in muscular disease." (PMID 26531141, 2015).
nemaline myopathy (12 papers, 2007 to 2025). Nemaline myopathy (NM) encompasses a large spectrum of myopathies characterized by hypotonia, weakness and depressed or absent deep tendon reflexes, with pathologic evidence of nemaline bodies (rods) on muscle biopsy. "In 2 individuals myopathy was associated with variants in the RYR1 gene, whereas in one individual nemaline myopathy caused by the KBTBD13 gene was diagnosed." (PMID 38758368, 2024). "From a histopathological point of view, the most prevalent form is nemaline myopathy, but based on genetics, RYR1 mutations are the most common genetic cause with many different phenotypic features." (PMID 32456280, 2020). "Nemaline myopathy with cores or core-like regions is caused by mutations in ryanodine receptor 1 (RYR1;) and Kelch repeat and BTB/POZ domains-containing protein 13 (KBTBD13;)." (PMID 22174871, 2011). "Most nemaline myopathies are caused by mutations in the components of the thin filaments, proteins which function downstream of RYR1 and calcium release to initiate contraction." (PMID 19197364, 2009). "The majority of these cases encompassed pathogenic RYR1 variants in core myopathy, NEB and ACTA1 in nemaline myopathy, and pathogenic MTM1 variants in CNM." (PMID 38982518, 2024). "Mutations in the ACTA1 gene, more commonly associated with nemaline myopathy, have been recently implicated in an autosomal dominant myopathy with both central and minicores; however, some patients in this pedigree had an associated cardiomyopathy, which is not a feature in RYR1-related CCD." (PMID 17504518, 2007). "In the present study, we investigated whether the expression of different groups of transcripts are similarly impacted in muscles from CM patients with AD and AR RYR1-related myopathies, SELENON-related MmD, KBTBD13-related nemaline myopathy and MTM1-related XL-MTM." (PMID 36196089, 2022). "Decreased RyR1 protein content has been reported in muscles from patients with AR RYR1 and SELENON-related MmD and MTM1-related XL-MTM19–23 but not in patients with nemaline myopathy." (PMID 36196089, 2022).
catecholaminergic polymorphic ventricular tachycardia (11 papers, 2013 to 2025). Catecholaminergic polymorphic ventricular tachycardia (CPVT) is a severe genetic arrhythmogenic disorder characterized by adrenergically induced ventricular tachycardia (VT) manifesting as syncope and sudden death. "The RyR2-G4663S mutation, which is at the corresponding residue as the RyR1-G4733E, was reported to be associated with catecholaminergic polymorphic ventricular tachycardia (CPVT)." (PMID 38159862, 2023). "In recent studies, S107, the RyR-specific derivative of JTV519, enhanced binding of FKBP12.6 to catecholaminergic polymorphic ventricular tachycardia (CPVT)-linked RyR2-R2474S mutant, and FKBP12 to the oxidized and hypernitrosylated RyR1." (PMID 23349825, 2013).
King-Denborough syndrome (11 papers, 2018 to 2025). A rare genetic non-dystrophic myopathy characterized by the triad of congenital myopathy, dysmorphic features and susceptibility to malignant hyperthermia. "Of note, similar mild myopathic manifestations have been previously reported in two other phenotypes closely linked to MH-associated RYR1 mutations, the King-Denborough syndrome and late-onset axial myopathy." (PMID 30788618, 2019). "The cause of King-Denborough syndrome is not fully understood, although some cases have been attributed to mutations in RYR1." (PMID 31081514, 2019). "This spectrum includes RYR1 variant-associated clinical phenotypes including King-Denborough syndrome, congenital neuromuscular disease with uniform type 1 fiber (CNMDU1), dusty core disease, rhabdomyolysis-myalgia syndrome, atypical periodic paralysis, and bleeding abnormalities." (PMID 33190635, 2020). "In addition, there is an expanding spectrum of RYR1-associated clinical phenotypes, including RYR1 rhabdomyolysis-myalgia syndrome, atypical periodic paralysis, and King-Denborough syndrome." (PMID 30155738, 2018). "On the other hand, RYR1 variants can determine different clinical phenotypes including interrelated conditions such as malignant hyperthermia susceptibility, exertional heat stroke, rhabdomyolysis-myalgia syndrome, King Denborough syndrome, and atypical periodic paralysis." (PMID 34827576, 2021). "Clinical phenotypes resulting from RYR1 variants are diverse and include interrelated conditions such as malignant hyperthermia (MH) susceptibility, exertional heat stroke, rhabdomyolysis-myalgia syndrome, King Denborough syndrome, and atypical periodic paralysis." (PMID 30406384, 2018). "A range of RYR1-RM clinical phenotypes has also emerged more recently and includes King Denborough syndrome, RYR1 rhabdomyolysis-myalgia syndrome, atypical periodic paralysis, congenital neuromuscular disease with uniform type 1 fibers, and late-onset axial myopathy." (PMID 30406384, 2018).
Myalgia (11 papers, 2015 to 2023). "Responses in older adults with RYR1 pathogenic variants are frequently in the form of exercise intolerance, myalgia, muscle cramps, and rhabdomyolysis." (PMID 33037202, 2020). "The spectrum of severity resulting from mutations in RYR1 is demonstrated, for instance, in skeletal muscles from patients suffering from diseases like atypical periodic paralysis and myalgia, and by the lethal multiple pterygium syndrome." (PMID 29543863, 2018). "Secondly, gain-of-function RYR1 variants might be an underrecognized cause of cramps and myalgia." (PMID 36751502, 2022). "Mutations in RYR1 gene leading to a defective RYR1 have been shown to cause neuromuscular disease and studies have shown an association between mutations in RYR1 causing disruptions in sarcoplasmic calcium regulation and development of unexplained rhabdomyolysis and/or exertional myalgia." (PMID 25853139, 2015). "Another important aspect concerns the repurposing of already existing drugs and the development of novel and more effective treatments for patients with RYR1-related cramps and myalgia." (PMID 36751502, 2022). "The proband's son's myalgia and elevated CK suggests that RYR1 p.Glu4106Alafs*8 has a dominant effect." (PMID 29178655, 2017). "RYR1 mutations are associated with a wide range of clinical phenotypes, collectively referred to as RYR1-related myopathies (RYR1-RM), that can include wheelchair and ventilator dependence, and dynamic symptoms such as exercise induced myalgias, heat stroke, and malignant hyperthermia." (PMID 32223895, 2020). "This patient presented with LGMW, hyperCKemia and myalgias with mild nonspecific muscle biopsy findings and muscle MRI within normal range and no cardiac alterations; these manifestations were considered within the spectrum of RYR1-related phenotypes." (PMID 35741838, 2022).
scoliosis (11 papers, 2007 to 2025). A congenital or acquired spinal deformity characterized by lateral curvature of the spine. "In this context, it should be noted that patients with some recessive RYR1 mutations often show scoliosis and joint contractures from birth." (PMID 41091627, 2025). "(2013) reported that 100% of the patients with recessive Ryr1 mutations presented symptoms and of these, 50% had scoliosis and 71% contractures that which appeared at birth, before the development major motor milestones such as deambulation." (PMID 41091627, 2025). "RYR1-RM-affected individuals can present with delayed motor milestones, contractures, scoliosis, ophthalmoplegia, and respiratory insufficiency." (PMID 33190635, 2020). "Regarding scoliosis, predominant or exclusive axial myopathy of late onset is a presentation of RYR1 gene pathogenic variants and can be present with or without cores on muscle biopsy." (PMID 37510264, 2023). "RYR1-RM can be inherited in a dominant or recessive manner and are slowly progressive with clinical manifestations including proximal muscle and facial weakness, joint contractures, scoliosis, ophthalmoplegia, and respiratory muscle weakness." (PMID 32381029, 2020). "In RYR1-RM, intracellular calcium dysregulation, post-translational modifications, and decreased protein expression lead to a heterogenous clinical presentation including proximal muscle weakness, contractures, scoliosis, respiratory insufficiency, and ophthalmoplegia." (PMID 32381029, 2020). "The significant degree of clinical (i.e., muscle weakness, breathing problems, scoliosis) and histopathological (i.e., minicores) overlap between SEPN1-RM and RYR1-RM might reflect molecular defects common to these two genetically distinct pathologies." (PMID 36450915, 2022).
ophthalmoplegia (10 papers, 2007 to 2024). Weakness or paralysis of at least one of the muscles controlling the movement of the eye. "In particular, patients with recessive RYR1 mutations often display involvement of extraocular muscles leading to ophthalmoplegia and or ptosis as well as involvement of respiratory muscles, often requiring assisted ventilation." (PMID 35238775, 2022). "Rare cases of autosomal recessive inheritance, with homozygous or compound heterozygous RYR1 mutations have been described presenting with severe congenital ophthalmoplegia and facial weakness in the setting of only mild skeletal myopathy." (PMID 33827624, 2021). "E-C uncoupling was also indicated by complete loss of Ca2+ conductance in recombinant mutant RyR1 channels expressing a Arg109Trp substitution previously associated with a MmD and ophthalmoplegia phenotype." (PMID 17631035, 2007). "Since our patients carrying RYR1 mutations do not show the typical signs of CMYP1B (e.g., ophthalmoplegia and severe hypotonia) and heterozygous RYR1 mutations were inherited from the unaffected fathers, we suppose that these variants are unlikely to be causative of their clinical condition." (PMID 39202332, 2024).
breast carcinoma (9 papers, 2017 to 2025). "PTMs on RyR1 have been linked to muscle dysfunction in diseases like breast cancer, rheumatoid arthritis, Duchenne muscle dystrophy, and aging." (PMID 39499505, 2024). "Here, we show that a syngeneic mouse model of OCIB (4T1 mammary tumor cells) leads to cachexia and skeletal muscle weakness associated with oxidation of the ryanodine receptor and calcium (Ca2+) release channel (RyR1)." (PMID 29312148, 2017). "Estrogen deprivation therapy for breast cancer resulted in maladaptive changes in skeletal muscle, consistent with the biochemical signature of dysfunctional RyR1 calcium channels." (PMID 38200207, 2024). "Here, we aimed to investigate the impact of AI-induced bone resorption on the skeletal muscle ryanodine receptor RyR1, and to explore the relationship between changes in muscle function at the molecular and clinical levels in women with breast cancer." (PMID 38200207, 2024). "The Ryanodine receptor 1 (RYR1) triggers the release of calcium, which causes a chain reaction that transforms ordinary breast cancer cells into cancer stem cells." (PMID 29443735, 2018). "Markers of oxidative stress on RyR1 are linked to FKBP12 dissociation and altered RyR1-mediated Ca2+ release, which also correlate with muscle weakness in breast cancer with bone metastases and ventilator-induced diaphragm dysfunction." (PMID 39499505, 2024). "Together with Theresa Guise we used a murine model of human breast cancer metastatic to bone to show that TGF-β released from the bone activated a pathway leading to oxidation of RyR1 in the neighboring skeletal muscle, rendering the channels leaky and promoting muscle weakness." (PMID 36647824, 2023). "Further, either inhibiting TGFβ directly (TGFβ receptor blockade [SD208] or TGFβ neutralizing antibody [1D11]) or indirectly (blocking TGFβ release from bone using a bisphosphonate zoledronic acid [ZA]) prevented RyR1 oxidation and restored muscle strength in mice with breast cancer bone metastases." (PMID 30918923, 2019).
Arrhythmia (8 papers, 2015 to 2026). Any cardiac rhythm other than the normal sinus rhythm. "On the other hand, RYR2 loss-of-function variants have also been associated with arrhythmias and RYR1 loss-of-function has been reported in skeletal myopathies." (PMID 40060969, 2025). "In conclusion, we presented an in-depth characterization of the recognition between a common CaM-binding region in RyR1 and RyR2 and two arrhythmia-associated CaM variants in their Ca2+-bound states." (PMID 36685279, 2022). "Mutations Q3970E/K in RyR1 are implicated in central core disease and equivalent RyR2 mutations in cardiac arrhythmia, which highlights the important Ca2+ sensing role for this residue." (PMID 35257661, 2022). "Increased RYR1 expression may contribute to HF progression, potentially through the mechanisms associated with calcium handling and arrhythmia development." (PMID 40060969, 2025). "To unravel the molecular mechanisms underlying the selective perturbation of the recognition between CaM and RyR1 or RyR2 in arrhythmia-associated conditions, we focused on a CaM binding target region comprising 31 amino acids with a very similar sequence in the two RyRs (known as CaMBD2)." (PMID 36685279, 2022). "Our results suggest that the ability of calmodulin to discriminate between RyR1 an RyR2 targets depends on kinetic discrimination and robust allosteric communication between Ca2+-binding sites (EF1-EF3 and EF3-EF4 pairs), which is perturbed in both N97I and Q135P arrhythmia-associated variants." (PMID 36685279, 2022). "For the adult RYR1-RM population a report of HCM and conduction/arrhythmias was provided by Petri in 2019." (PMID 34827576, 2021).
cardiomyopathy (8 papers, 2007 to 2025). A disease of the heart muscle or myocardium proper. "Even if there was crossover in the function of RYR1 to cardiac tissue, the phenotype one might expect would be cardiomyopathy." (PMID 34528764, 2021). "Several calcium ion channels involved in cardiomyopathies are associated with TOP2B peaks including the voltage-dependent calcium channel CACNA1C, the sarcoplasmic reticulum calcium release channel RYR1, and the Na+/Ca+ exchanger and calcium anti-porter SLC8A1." (PMID 26459242, 2015). "Structural cardiac abnormalities other than mitral valve prolapse have rarely been reported, but cardiomyopathies are not a feature of CCD associated with RYR1 mutations." (PMID 17504518, 2007). "An associated cardiomyopathy has not been reported in typical CCD due to mutations in the RYR1 gene; however, cardiomyopathies associated with mutations in the MYH7 and the ACTA1 genes may feature central cores on muscle biopsy but do not share the typical clinical features of CCD." (PMID 17504518, 2007). "The phenotype for each ryanodine receptor disease seems to be unique to the receptor and tissue type; cardiomyopathy is not reported in the phenotypic spectrum of RYR1‐RM; and skeletal myopathy is not reported in the phenotype of RYR2 disease." (PMID 34528764, 2021).